GPX4 (glutathione peroxidase 4)
Diseases named in the same sentence as GPX4 in open-access papers (continued):
Sharing a sentence is not in itself a finding about the gene and the disease.
cancer (continued). "It was reported that the EMT-like or persister cell state in cancer cells is highly dependent on GPX4 activity for survival." (PMID 35406721, 2022). "It has been found that intracellular fumaric acid aggregation causes succination of GPX4 at cysteine 93, resulting in a decrease in GPX4 activity and sensitizing cancer cells to ferroptosis inducers." (PMID 36105219, 2022). "Previous studies have reported that inducing ferroptosis by inhibiting intracellular GPX4 is a potential approach for the treatment of cancers in women." (PMID 35422066, 2022). "In contrast to CD8(+) T cell killing to cancer cells, T regulatory (Treg) cells exhibit immune tolerance and inhibit antitumor immunotherapy, and high levels of GPX4 in Treg cells prevent lipid peroxidation and ferroptosis." (PMID 36289191, 2022). "Cystine/glutamate antiporter system χc–/GSH/GPX4 axis is a classical pathway protecting against ferroptosis, in which GPx4 is considered to be the key regulator in cancer cells and neurons." (PMID 35318305, 2022). "Still, ferroptosis is a unique, irreversible cell death mechanism such that triggering ferroptosis will induce death in therapy-resistant cancer due to cancer cells relying on GPx4 for survival." (PMID 36591540, 2022). "Deletion of FSP1 in cancer cells results in increased lipid ROS even in the presence of functional GPX4, and overexpression of FSP1 blocks propagation of lipid ROS in RSL3-treated cells." (PMID 35065965, 2022). "Cancer cells seem to have adopted these pathways, and overexpression of GPX4 is a feature of many cancers, offering protection against oxidative stress-induced cell death." (PMID 34983949, 2022). "Conversely, inhibition of mTORC1 decreases GPX4 expression and facilitates ferroptosis sensitivity in cancer cells." (PMID 36289191, 2022). "As a metabolic checkpoint, GPX4 in cancers was found to protect activated CD8+ T cells and Treg cells from uncontrolled ferroptosis without compromising their function." (PMID 35620733, 2022). "Accordingly, increasing evidence encourages the rational combination of GPX4 inhibitors and current chemotherapies as a dual therapy in a diverse range of cancer types." (PMID 35453641, 2022). "Traditional chemotherapeutics can upregulate GPX4 and system Xc‐ to inhibit cancer cell death and ferroptosis." (PMID 36317423, 2022). "As the key regulator of ferroptosis, GPX4 has attracted considerable attention in the fields of cancer, cardiovascular, and neuroscience research in the past 10 years." (PMID 35647032, 2022). "Remarkably, cancer cells increase the intake of Se and Sec to potentially control GPX4 levels and warrant themselves resistant to ferroptosis." (PMID 36358931, 2022). "When GPX4 is inactivated via direct or indirect targeting, this can result in the induction of ferroptotic cancer cell death." (PMID 34983546, 2022). "Recently, it was proposed a new model for antioxidant enzymes involved in defense against lipid peroxidation in cancer: GPx4 in the cytosol and mitochondria, FSP1 on the plasma membrane, and DHODH in mitochondria." (PMID 35255427, 2022). "Conversely, overexpression of GPX4 counteracts RSL-3 induced ferroptosis in several different cancer cell lines." (PMID 35531466, 2022). "Cancer cells that survive from targeted therapy or chemotherapy are efficiently eliminated by inhibiting glutathione peroxidase 4 (GPX4), the major antioxidant enzyme for reducing oxidated lipids." (PMID 34685686, 2021). "It has been reported that the GPX4 gene inhibits ferroptosis in cancer cells, as also found in the present survival analysis." (PMID 33706760, 2021). "To systematically analyze the significance of the FPscore in pan-cancer, we evaluated the expression of the immune check-points and GPX4." (PMID 34512160, 2021).
cancer (continued). "The discovery of two other known antioxidant pathways not only indicates that GPX4 is not the only ferroptosis suppressor but also partially reveals the ferroptosis resistance of some cancer cell lines to the targeted system xc--GPX4 axis." (PMID 34815796, 2021). "GPx4 is widely accepted as a primary regulator of ferroptosis, however, the sensitivity of cells to GPx4 inactivation-induced ferroptosis varies greatly across cancer types." (PMID 34611144, 2021). "Our data thus demonstrate that Gpx4 largely contributes to the stimulatory role of PTENα in cancer immune escape." (PMID 34446716, 2021). "Moreover, an influence of selenoprotein polymorphisms on the risk of breast (Gpx1, SelF, SelP) or colorectal (Gpx4, TrxR1, and TrxR2, SelP, SelF, and SelS) cancer was also found, which could indicate their important role in the etiology of these types of cancer." (PMID 34068374, 2021). "Ferroptosis is a novel sort of cell death that occurs when GPX4 is inhibited by a reduction in GSH levels in RAS-mutant cancer cells." (PMID 34441564, 2021). "A pan-cancer analysis on the association of CALU with HSPA5, GPX4 and SLC7A11 further confirmed the potential involvement of CALU in the regulation of ferroptosis." (PMID 34150647, 2021). "A recent study has found that the SRC gene is one of the targeting sites of GPX4, the differential expression of which regulates cell proliferation, cancer progression, apoptosis, and ferroptosis." (PMID 34568341, 2021). "It reported that treatment of cancer cells with GPX4 inhibitors resulted in rapid depletion of N-carboxyl-L-aspartic acid, a pyrimidine biosynthesis intermediate, accompanied by the production of uridine." (PMID 34778060, 2021). "Chemotherapy-resistant GBM and other cancer cells, especially those that are mesenchymal and metastatic, are relatively more sensitive to ferroptosis induced by glutathione peroxidase-4 (GPX4) inhibition." (PMID 34804371, 2021). "Here, the authors reveal that cystine uptake promotes GPX4 synthesis by activating mTORC1 and show that cancer cells are sensitized to ferroptosis by mTORC1 inhibition." (PMID 33707434, 2021). "Based on these mechanisms, especially for the Fenton reaction and suppressing activity of GPX4, ferroptosis has provided a new idea for cancer therapy." (PMID 34987385, 2021). "The results showed that in clinical samples, TIPE and GPX4 were expressed at higher levels in cancer tissues than in adjacent tissues (p < 0.05)." (PMID 34601499, 2021). "In the condition of cysteine depletion, the synthesis of GSH in cancer cells is blocked, the activity of GPX4 is reduced, and the redox imbalance in the cell leads to a large accumulation of lipid peroxides and eventually ferroptosis." (PMID 34917232, 2021). "Erastin and xCT inhibitors as a strategy to inhibit selenium uptake and GPX4 production in cancer cells." (PMID 33672555, 2021). "RSL3 is a well-known ferroptosis inducer, which can activate the ferroptosis process in multiple cancer cells through irreversibly inducing the inactivation of ferroptosis key regulatory protein GPX4." (PMID 33819186, 2021). "Our data, therefore, suggest that pharmacologic inhibition of mTORC1 sensitizes cancer cells to GPX4 inhibition-induced ferroptosis." (PMID 33707434, 2021). "In cancer cells, selenium compounds interfere with the selenium uptake, selenocysteine biosynthesis and the production of selenoproteins, such as GPX4, consequently abrogating cell protection against ferroptosis." (PMID 34041026, 2021). "Further understanding of the structure, location, and function of GPX4 is essential for the development of cell death therapies for cancer patients." (PMID 34742351, 2021). "GPX4-mediated regulation of ferroptosis is also a survival mechanisms of cancer cells, which can increase GPX4 levels through the induction of selenophosphate synthetase 2 (SEPHS2), an enzyme involved in SeCys biosynthesis." (PMID 34948472, 2021).
cancer (continued). "Drug-tolerant persister cancer cells have characteristics of a high mesenchymal cell state that lead to dependency on a lipid peroxidase pathway involving glutathione peroxidase 4 (GPX4)." (PMID 34749765, 2021). "Our fundamental understanding of cyst(e)ine and mTORC1 regulation of GPX4 protein synthesis also has important implications for cancer therapies." (PMID 33707434, 2021). "Regarding GPX4’s role in cancer, GPX4 is overexpressed in a variety of cancers, and Gpx4+/− mice exhibit delayed lymphomagenesis compared with their wild-type counterparts." (PMID 33891303, 2021). "The GPX4 expression in cancer tissues exceeded than that in normal tissues and was negatively correlated with the prognosis of patients with all types of cancer." (PMID 33574983, 2021). "Conceivably, the abundance of GSH determines the catalytic efficiency of GPX4 and the sensitivity of cancer cells to ferroptosis." (PMID 34815796, 2021). "There are several GPX4 inhibitors in development although it remains to be determined if their therapeutic index will be good enough to permit their use in cancer patients." (PMID 34429409, 2021). "So far, ferroptosis has been thought to induce cancer cell oxidative damage by controlling the phospholipid hydroperoxide-reducing enzyme GPX4." (PMID 34627266, 2021). "Erlotinib, vemurafenib, and lapatinib eradicate PC9, A375, and BT474 cell lines through GPX4 inhibition, respectively, indicating the clinical potential of GPX4 inhibitors for dormant cancer therapy." (PMID 34685686, 2021). "Dihydroartemisinin augmented GPX4 inhibition-induced ferroptosis in some cancer cells in both in vitro and in vivo models by the inducible knockout of GPX4." (PMID 35035355, 2021). "While most cancer cells depleted of GPX4 fail to grow in vivo, some cells can survive despite a lack of GPX4 expression." (PMID 33801564, 2021). "A recent study showed that drug-resistant cancer cells in a high-mesenchymal cell state were sensitive to ferroptosis induced by GPX4 inhibition or statin treatment." (PMID 34303383, 2021). "Inhibition of both the Nrf2 pathway and GPx4 activity (or glutathione pathway) is an attractive strategy to specifically target cancer cells." (PMID 34202320, 2021). "It was reported that GPx4 inhibition resulted in ferroptotic death in therapy-resistant cancer cells." (PMID 34439326, 2021). "GPX4, as an oncogene, inhibits the ferroptosis effect of cancer cells, while GPX4 inhibition can enhance the anticancer effect of cisplatin." (PMID 34059009, 2021). "To investigate the relationship between TIPE and GPX4 expression and their clinical value, we evaluated their expression at the protein level with immunohistochemistry in the adjacent and cancer tissues of five patients." (PMID 34601499, 2021). "Further studies are required to define the therapeutic window of GPX4 inhibition in cancer treatment and to explore techniques to target GPX4 locally in tumors for radiosensitization." (PMID 33891303, 2021). "Many types of cancer cells that are resistant to chemotherapy and certain targeted therapies appear to be sensitive to ferroptosis induced by GPX4 inhibition." (PMID 33611811, 2021). "This study found GPX4 is an essential regulator of ferroptotic cancer cell death; before that, GPX4 had been proved to protect against lipid peroxidation and oxidative stress damage." (PMID 34150654, 2021). "Several mechanisms of GPX4 regulation in cancer cells have been observed including regulation by heat shock 70 kDa protein 5 (HSPA5), a molecular chaperone found primarily in the endoplasmic reticulum." (PMID 33499222, 2021). "It seems that glutathione peroxidase 4 (GPX4) upregulation prevents ferroptosis in cancer cells to mediate CP resistance." (PMID 33921908, 2021). "At the same time, CO can inhibit the expression of cystathionine β synthase (CBS) and glutathione peroxidase 4 (Gpx4), increasing the sensitivity of cancer cells to DOX by enhancing the effect of ferroptosis." (PMID 34949202, 2021).
cancer (continued). "Together, our results reveal a regulatory mechanism to coordinate GPX4 protein synthesis with cyst(e)ine availability and suggest using combinatorial therapy of mTORC1 inhibitors and ferroptosis inducers in cancer treatment." (PMID 33707434, 2021). "A recent article published in Cell Research also pointed out that ionizing radiation (IR) induced an adaptive response involving SLC7A11 or GPX4 induction that promoted cancer cell survival." (PMID 34040532, 2021). "DUB inhibitor-mediated induction of GPX4 proteasomal degradation has been suggested as a potential anticancer therapy because cancer cell lines and primary cancer cells are sensitive to ferroptosis." (PMID 33919439, 2021). "Its inhibition through brequinar sodium (BQR) induces mitochondrial-related ferroptosis in cancer cells with low expression of GPX4 and enhances the anticancer effect of ferroptosis inducers in cancer cells with a high expression of GPX4." (PMID 34359572, 2021). "Previous work has suggested that altered expression of key negative regulators of ferroptosis including SLC7A11 and GPX4 has a significant bearing on cancer progression." (PMID 34803511, 2021). "The FPscore was significantly associated with GPX4, PD-L1, PD-1, and CTLA4 in many cancers, including HNSCC." (PMID 34512160, 2021). "Accordingly, deficiencies in a host of NRF2 targets, including GPX4, SLC7A11 and FTH1/FTL, are also capable of predisposing cells to succumb to proferroptotic agents in many cancer types." (PMID 35118067, 2021). "Heat shock protein family A member 5 (HSPA5, best known as BIP) is a molecular chaperone in the endoplasmic reticulum, which directly binds GPX4 to prevent its degradation, thereby inducing cancer cell resistance to ferroptosis." (PMID 34742351, 2021). "Certain cancer cells, such as drug-tolerant persister cancer cells or therapy-resistant high-mesenchymal ones, are highly dependent on GPX4 activity, thereby exposing potential vulnerabilities for therapeutic targeting." (PMID 33891303, 2021). "As expected, activation of Nrf2 pathways confers resistance to GPX4 inhibitor induced ferroptosis in cancer cells." (PMID 34945503, 2021). "Inducers of ferroptosis such as the glutathione depleting agent Erastin and the GPX4 inhibitor Rsl-3 are being actively explored as potential therapeutics in various cancers, but the factors that determine their sensitivity are poorly understood." (PMID 33672555, 2021). "Current studies on ferroptosis-targeted cancer therapy have focused on antioxidant defenses, particularly the system xc- - GPX4 axis." (PMID 34815796, 2021). "The ferroptosis inducer, RSL3, triggers ferroptosis in various cancers by inhibiting GPX4 expression." (PMID 34987700, 2021). "As previous studies suggested that GPX4 inhibition induced ferroptosis, we rationalized that an alternative way to lead to cancer cell death by inducing ferroptosis would be through ubiquitination of GPX4 to reduce abundance of GPX4." (PMID 33472669, 2021). "The increase in DHODH activity increased the resistance of cancer cells to ferroptosis in cell lines overexpressing GPX4 and FSP1." (PMID 34815796, 2021). "In different immune cell-derived cancer cell lines, it has been shown that GPx4 and GPx1 act as important inhibitors of cellular 5-LOX activity." (PMID 31765890, 2020). "Some of them inhibit ferroptosis to protect cancer cells from cell death, such as GPX4, nuclear factor erythroid 2-related factor 2 (NRF2), CD44v." (PMID 33665167, 2020). "Because of the upregulated expression of ACSL4 yet downregulated level of and FPN-1 and GPX4, 4T1 cell line demonstrated high ferroptosis sensitivity and was utilized for anti-cancer study." (PMID 32312987, 2020). "Ferroptosis induction by inhibiting GPX4 is expected to become a most promising therapeutic strategy for promoting cancer cell death and treating some cancers." (PMID 33511116, 2020).
cancer (continued). "Cancer cells become strongly dependent on GPX4 and on the cystine/glutamate antiporter (system Xc-) to import extracellular cysteine, essential for GSH biosynthesis." (PMID 32295216, 2020). "More importantly, the diversity of targeted therapies causing this shared GPX4 dependence suggests that lipid remodeling leading to PUFA enrichment of phospholipids might be a common mechanism associated with therapy resistance that could be pursued as therapeutic target in multiple types of cancer." (PMID 32577235, 2020). "The molecular chaperone HSPA5 and HSP90 regulate ferroptosis through modulation of GPX4 degradation in human cancer cells." (PMID 32596160, 2020). "GPX4 is a pharmacological target in cancer, and its inhibition has been found to induce cancer cell death by the accumulation of lipid hydroperoxides." (PMID 33167334, 2020). "Nowadays, most therapies achieve the effect of eliminating cancer cells by directly or indirectly inhibiting GPX4 and system XC− or promoting ROS generation." (PMID 33665167, 2020). "The significance of GPX4 in treatment resistance of cancer cells was revealed in studies on drug‐tolerant persister cells from several types of cancer that were found to be vulnerable to inhibition of GPX4." (PMID 32027447, 2020). "We conducted a series of validation tests and found that cancer cells treated with curcumin for 48 hours showed increased ROS levels and significantly reduced GPX4, cell lipid peroxidation, and iron accumulation levels." (PMID 33294119, 2020). "Further insight into the roles of other antioxidant systems such as Nrf2 and GPX4, and how they act both alone and together, will provide important clues into more effective therapies for cancer patients." (PMID 33072762, 2020). "Increased GPX4 degradation has been demonstrated to play an important role in ferroptotic cancer cell death." (PMID 32596160, 2020). "Activation of the Nrf2-ARE pathway thus contributed to the resistance of cancer cells to GPx4 inhibition, and inhibition of this pathway reversed the resistance of cancer cells to ferroptosis." (PMID 33343809, 2020). "The abnormal expression of GPX4 is shown to link with various human diseases including cancer and chronic disease." (PMID 32103754, 2020). "Given the therapeutic promise for inducing ferroptosis in drug-resistant cancers, a potent GPX4 inhibitor is paramount." (PMID 33425751, 2020). "For example, GPX4 negatively correlated with prognosis of pan-cancer patients as the low methylation level at the upstream site leads to its higher expression in cancer tissues." (PMID 33134164, 2020). "Unsurprisingly, human GPX4 knockout cancer cells inoculated into immunodeficient mice initially failed to strive, presumably due to an increase in the ferroptotic demise of the cells." (PMID 33235217, 2020). "Inhibition of FSP1 substantially synergized with inhibitors of GPX4 in ferroptosis induction in cancer cells." (PMID 32340261, 2020). "GPX4 is a major regulator of this form of programmed cell death, which is further exacerbated in cancers where recent studies have shown GPX4 as essential in some tumors." (PMID 33050144, 2020). "Glutathione peroxidase 4 (GPX4) is known as the central regulator of ferroptosis; a decrease in GPX4 expression is a signal of ferroptosis Ferroptosis is involved in various diseases, including cancer, and sorafenib induces ferroptosis in HCC." (PMID 33059615, 2020). "GPX4 is one of the most important antioxidant enzymes and an essential regulator of ferroptotic cancer cell death." (PMID 31956296, 2020). "Other QRs, with similar or higher Km values for quinones, are also putative targets for cancer treatment combined with GPX4 inhibitors." (PMID 33167334, 2020). "Using various cell lines and publicly available CTRP data, we confirmed that mesenchymal-high cancers exhibit enhanced sensitivity to ferroptosis inducers, especially the GPx4 inhibitors." (PMID 31527591, 2019).